CHEK2 (checkpoint kinase 2)
Diseases named in the same sentence as CHEK2 in open-access papers (continued):
Sharing a sentence is not in itself a finding about the gene and the disease.
pilocytic astrocytoma (1 paper, 2018). Pilocytic astrocytoma is a rare subtype of low-grade glioma of the central nervous system characterized by a well circumscribed, often cystic, brain tumor with a discrete mural nodule and long, hair-like projections that extend from the neoplastic astrocytes. "Histologic examination showed pilocytic astrocytoma (PA) with anaplasia, and molecular characterization revealed FGFR1 duplication with additional variants of unknown significance in several genes (ARID1A, ARID1B, CHEK2, EPHA5, and MLL2)." (PMID 29610389, 2018).
polyp (1 paper, 2020). A usually exophytic mass attached to the underlying tissue by a broad base or a thin stalk. "MLH1 was the most frequently mutated gene, as it was found to be mutated in four early-onset sporadic CRC patients (44.4% or 4/9), and CHEK2 (22% or 2/9) was found to be mutated in two polyp patients." (PMID 33260537, 2020). "This novel CHEK2 variant has not previously been reported in polyp patients, but the CHEK2 mutation had been found to be common in other sporadic CRC groups." (PMID 33260537, 2020).
sensitive (1 paper, 2016). "MEC1 and RAD53 (radiation sensitive mutant 53, human CHEK2) were initially identified in Saccharomyces cerevisiae as genes required for the S and G2 checkpoints that are induced by DNA replication inhibition and DNA damage, respectively." (PMID 28036033, 2016).
serous borderline ovarian tumor (1 paper, 2022). "The only relevant diagnosis was the serous borderline ovarian tumor in the CHEK2 mutated patient, who underwent RRS for her genetic mutation as there was no preoperative suspicion of cancer, no personal history of BC or family history of EOC." (PMID 36553061, 2022).
supraglottic cancers (1 paper, 2020). "Of note, cancer related proteins RB1, CHEK2, CCNE1, S6 and PIK3CA were higher in the supraglottic cancers, whereas PDL1 was higher in the glottic cancers." (PMID 33396315, 2020). "Cell cycle proteins including CHEK2, CCNE1, and phosphorylated RB1 were expressed at higher levels in the supraglottic cancers, which may indicate a disruption in the G1/S transition." (PMID 33396315, 2020).
T-cell prolymphocytic leukemia (1 paper, 2015). A slow-growing type of leukemia (blood cancer) in which too many lymphocytes are found in the bone marrow and/or blood. "Further, CHEK2 mutations (together with other genes implicated in DNA repair) were described as part of mutational landscape of T-cell prolymphocytic leukemia." (PMID 26506619, 2015).
tongue cancer (1 paper, 2016). A malignant neoplasm affecting the tongue. "The treatment of SCC-4 human tongue cancer cells with Gyps induced checkpoint kinase 2 (Chk2) expression." (PMID 27708693, 2016).
tubular adenoma (1 paper, 2022). A usually polypoid neoplasm arising from the glandular epithelium. "Two CHEK2 variant carriers underwent colonoscopy, which yielded the finding of tubular adenoma in one case." (PMID 35938029, 2022).
type 2 diabetes (1 paper, 2024). "CHEK2 variations have been associated with an increased risk of type 2 diabetes in multiple populations." (PMID 37945898, 2024).
uterine corpus endometrial carcinoma (1 paper, 2021). A endometrial carcinoma (disease) that involves the body of uterus. "Somatic mutations of CHEK2 significantly increased HRD in uterine corpus endometrial carcinoma (UCEC, FDR < 3.3×10−7)." (PMID 34572800, 2021).
cancer (749 papers, 2001 to 2026). A tumor composed of atypical neoplastic, often pleomorphic cells that invade other tissues. "A reduced cancer risk is particularly well established for the CHEK2 p.I157T variant, prompting the updated guidelines." (PMID 41756456, 2026). "Three of these patients died due to disease progression, and two had a family history consistent with the CHEK2 cancer predisposition spectrum." (PMID 41919248, 2026). "This shift reflects evidence that some missense variants carry a lower cancer risk than CHEK2 loss-of-function variants." (PMID 41756456, 2026). "To assess an association between CHEK2 pLoF variants and HMs, we performed univariate and multivariate logistic regression for sex, age, CHEK2 status, and smoking status after filtering out UKBB participants with non-CHEK2 likely germline cancer risk alleles." (PMID 40335619, 2025). "CHEK2, a classic cancer susceptibility gene, whose harmful mutations are associated with multiple types of cancer." (PMID 40568577, 2025). "Mutations in the CHEK2 gene have been linked to an increased risk of developing certain types of cancer, including breast, prostate, and colorectal cancer." (PMID 39996890, 2025). "Deleterious germline CHEK2 variants are considered moderate penetrance risk alleles for breast and prostate cancers, and possibly other solid organ malignancies." (PMID 40335619, 2025). "CHEK2 deleterious variants are now among the most frequently detected alterations in multigene cancer panel testing." (PMID 40492861, 2025). "We found a double mutation (DM) in 6 patients, with one carrying a DM in MUTYH and the other 5 harboring mutations in MUTYH and other cancer susceptibility genes (CHEK2, BRIP1, MLH1, and BRCA1)." (PMID 41001951, 2025). "CHEK2 encodes the checkpoint kinase CHK2 involved in DNA damage repair and is implicated as a risk for cancer development." (PMID 40563612, 2025). "Although CHEK2’s involvement in cancer susceptibility is becoming increasingly clearer, nothing is known about how DNA repair gene polymorphisms combine to influence this risk." (PMID 40507526, 2025). "More studies are needed to understand if LR variants in CHEK2 are genetic modifiers associated with cancer risk." (PMID 39745704, 2025). "The most frequently mutated gene in the cohort was CHEK2, identified in 9% of patients, indicating its prominent role in hereditary cancer predisposition in this population." (PMID 41294693, 2025). "In this cohort study, individuals with 2 LR variants in CHEK2 had a cancer phenotype similar to those with a single LR variant and similar to WT controls." (PMID 39745704, 2025). "The patient's genetic findings, including the presence of an atypical EWSR1::FLI1 fusion and a possible cancer predisposition due to a CHEK2 variant, further complicate the clinical picture, necessitating a more nuanced treatment approach." (PMID 40630716, 2025). "The role of CHEK2 in germline predisposition to cancer is still a topic of debate, and further investigations are needed to determine its precise involvement in in-vivo carcinogenesis." (PMID 40177144, 2025). "This cohort study characterizes the cancer phenotype among individuals with biallelic CHEK2 variants, specifically variants that have been associated with lower cancer risk in the heterozygous state." (PMID 39745704, 2025). "Individuals with a CHEK2 PV and an LR variant had a similar cancer phenotype to individuals with 2 PVs." (PMID 39745704, 2025). "Among individuals with a PV and LR variant, 95.0% had a prior cancer diagnosis, similar to those with 2 PVs in CHEK2 (95.2%)." (PMID 39745704, 2025). "Here, we show that CHEK2 LR variants are likely associated with a modified cancer phenotype when individuals also harbor a CHEK2 PV." (PMID 39745704, 2025). "eFigure 3 in Supplement 1 displays the ORs for the MyCode cohort for all-variant, PTV, and PMV CHEK2 groups for all specific types of cancer from all organ system groupings of cancer ICD codes." (PMID 41396600, 2025).
cancer (continued). "CHEK2 was initially identified as a cancer susceptibility gene in Li Fraumeni syndrome, first reported in 1999." (PMID 40492861, 2025). "In this investigation, relatedness-adjusted, Bonferroni-corrected genomic ascertainment of 2 population-based, exome-sequenced, electronic health record–linked cohorts was used to quantify cancer risk and survival from P/LP germline variants in CHEK2." (PMID 41396600, 2025). "eFigure 4 in Supplement 1 displays the ORs for the UKBB cohort for the all-variant, PTV, and PMV CHEK2 groups for all specific types of cancer from all organ system groupings of cancer ICD codes." (PMID 41396600, 2025). "CHEK2, a well-established breast cancer susceptibility gene with moderate-risk associations, was also reported for multiple other cancer types." (PMID 40034715, 2025). "In a study of 4008 Polish cancer patients, positive associations were identified between the CHEK2 I157T missense mutation and thyroid, breast, and prostate cancer." (PMID 40492861, 2025). "This case-control study evaluates the prevalence, cancer risk, and survival among adults with pathogenic or likely pathogenic germline variants in CHEK2." (PMID 41396600, 2025). "For example, individuals can be monitored and regularly screened for cancer-related phenotypes associated with CHEK2 and STK11 (individual 1) and SDHA (individual 4)." (PMID 40195116, 2025). "Overall, a germline pathogenic variant (gPV) in a cancer predisposing gene was identified in 9.7% of individuals (CHEK2, FANCM, NF1, POT1 and PTEN) and a candidate variant in 4.2% of individuals (HOXB13, MAX and RECQL4)." (PMID 39979679, 2025). "The risk of cancer associated with CHEK2 missense variants is relatively low, with some notable exceptions." (PMID 40283643, 2025). "Are CHEK2 low-risk (LR) variants p.I157T, p.S428F, and p.T476M associated with cancer phenotype when in a biallelic state similar to biallelic pathogenic and likely pathogenic variants (PVs) in CHEK2?" (PMID 39745704, 2025). "In this cohort study including 3783 individuals with CHEK2 PVs and LR variants, individuals with 2 LR variants in CHEK2 had a cancer phenotype similar to those with a single LR variant and wild-type controls." (PMID 39745704, 2025). "This retrospective observational cohort study examining cancer phenotype by CHEK2 genotype was conducted at a single diagnostic genetic testing laboratory." (PMID 39745704, 2025). "In this case-control study, we evaluated cancer risk and survival in individuals with heterozygous CHEK2 variants using the novel genome-first approach in 2 well-powered cohorts." (PMID 41396600, 2025). "In this case-control study, we used genomic ascertainment to quantify cancer risk for individuals with heterozygous germline pathogenic or likely pathogenic (P/LP) CHEK2 variants." (PMID 41396600, 2025). "CHEK2 mutations are associated with breast, prostate, kidney, and possibly other cancers, but the presence of variants of uncertain significance and variable penetrance complicates the confirmation of their role in specific cancers." (PMID 41331641, 2025). "What is the cancer risk in adults who harbor a pathogenic or likely pathogenic germline CHEK2 variant when ascertained genomically?" (PMID 41396600, 2025). "Using gnomAD non‐cancer subjects as a control group, potential germline pathogenic CHEK2 variants were associated with a 2.8‐fold increased risk (95% CI 1.8–4.6, p < 0.01) of AGCT." (PMID 38898688, 2024). "CHEK2 missense variants have been linked to breast and other cancers; however, ∼90% are classified as variants of uncertain significance." (PMID 39642869, 2024). "Mutations in the CHEK2 gene have been found to be correlate with various cancers, particularly hereditary cancers like breast and colorectal cancer." (PMID 38242891, 2024). "In this study, we used genomic ascertainment to quantify cancer risk for heterozygotes with germline pathogenic CHEK2 variants." (PMID 39371170, 2024).
cancer (continued). "Our previous studies conducted on a White population showed a higher cancer risk in ATM + CHEK2 or two CHEK2 PVs than single gene variants." (PMID 39594831, 2024). "The most frequently mutated gene in CHEK2-deficient cancers was PIK3CA (n = 4 cancers, three cancer types)." (PMID 38848470, 2024). "Genomic ascertainment was used to quantify cancer risk in CHEK2 germline pathogenic variant heterozygotes." (PMID 39371170, 2024). "Cancer associations for coding variants in ATM and CHEK2 were evaluated using whole-exome sequence data from UK Biobank linked to cancer registration data (348 488 participants), and analysed both as a retrospective case-control and a prospective cohort study." (PMID 39209703, 2024). "Consistent with its cell-cycle checkpoint role, both germline and somatic variants in CHEK2 have been linked to breast and other cancers." (PMID 39642869, 2024). "Additional CHEK2 variants that impair protein function have been identified in the germline of individuals with cancer and are associated with the development of cancer." (PMID 39146382, 2024). "Taken together, our study provides additional evidence that impairment of CHEK2 does not result in HRD, which likely explains the inefficiency of PARPi treatment of CHEK2-deficient cancers." (PMID 38848470, 2024). "The CHEK2 mutation, which impairs DNA repair mechanisms, further increases the patient’s risk for cancer development." (PMID 39221315, 2024). "In summary, we quantified cancer risk and survival in CHEK2 heterozygotes using the novel genome-first approach in two well-powered cohorts." (PMID 39371170, 2024). "In this study, we aimed to determine the germline CHEK2 variation frequency among Turkish cancer patients and individuals with cancer predisposition and evaluate the variants’ effects on CHK2 protein function using a new statistical approach." (PMID 39594831, 2024). "Our analyses demonstrate that ATM and CHEK2 PTVs are associated with increased risks of a wide range of cancers, with the overall cancer risk being higher for ATM." (PMID 39209703, 2024). "Our findings will help to enhance the evaluation and management of cancer predisposition associated with CHEK2 in Türkiye and other regions that have significant Turkish populations." (PMID 39594831, 2024). "This study aims to delineate the spectrum of CHEK2 variants among individuals with possible cancer predisposition risk or with hereditary cancer backgrounds in Türkiye." (PMID 39594831, 2024). "CHEK2 is a moderately penetrant gene that has been studied for its association with cancer predisposition." (PMID 39146382, 2024). "Carriers of pathogenic germline CHEK2 variants have an increased risk of breast, prostate, colon, kidney, thyroid, and potentially other cancers." (PMID 38898688, 2024). "Current cancer risk estimates and management guidelines are based on the CHEK2 1100delC frameshift mutation." (PMID 38898688, 2024). "They analyzed the genomes of 16 cancers from 9 individuals homozygous for the most common loss-of-function (LoF) gPV in CHEK2 (c.1100del)." (PMID 38950525, 2024). "The median number of LSTs and tAIs in CHEK2-deficient cancers was 3 (range = 1-12) and 7 (range = 0-22), respectively." (PMID 38848470, 2024). "We found that the FLT3LG exGS was largely explained by trans-pQTL that lie in established cancer risk genes involved in the regulation of cell division and DNA repair (CHEK2 [22:28695868:AG:A], ATM [11:108267276:T:C], and TERT [5:1293971:C:T])." (PMID 38750076, 2024). "The odds ratios and Bonferroni-corrected p-values for the association between CHEK2 heterozygotes for organ system groupings of cancer ICD codes are shown." (PMID 39371170, 2024). "The median LST and tAI counts in cancers from individuals heterozygous for CHEK2 gPVs were 4 (range = 0-16) and 8.5 (range = 0-26), respectively, which is comparable to the counts observed in our CHEK2-deficient cancers." (PMID 38848470, 2024).
cancer (continued). "Cancers from individuals heterozygous for CHEK2 gPVs presented with mutational signatures SBS1 and/or SBS5 in 12/28 (43%; P = 1) and 12/28 (43%; P < .05) cancers, respectively." (PMID 38848470, 2024). "Another CHEK2 gene variant implicated as elevating low-penetrance cancer risk is the intronic substitution c.444+1G>A (IVS2+1G>A), which modifies the splicing acceptor site." (PMID 39125905, 2024). "Loss of function mutations in the checkpoint kinase gene CHEK2 are associated with increased risk of breast and other cancers." (PMID 39146382, 2024). "Recent work has demonstrated that most missense P/LPs in CHEK2 have a cancer-risk phenotype similar to loss-of-function mutations and are distinct from the three low-risk variants." (PMID 39594831, 2024). "In a recent publication, the American College of Medical Genetics and Genomics (ACMG) reported that CHEK2 specific clinical practice should be used in the management of CHEK2-associated cancer risks." (PMID 39594831, 2024). "Ninety-four hereditary cancer predisposition genes were analyzed through next-generation sequencing, revealing two germline CHEK2 missense variants (c.962A > C, p.E321A and c.470T > C, p.I157T), which segregated with TC in each FNMTC family." (PMID 38367672, 2024). "ATM and CHEK2 are included on many cancer gene panels used in family cancer clinics, and the risk estimates from these analyses can inform genetic counselling for carriers." (PMID 39209703, 2024). "CHEK2 is the third gene, in which we most frequently identified variants in association with cancer." (PMID 39148954, 2024). "Analyses of the resulting data indicate that it will be useful for developing models to predict the cancer risk in individuals who inherit any CHEK2 variants." (PMID 39146382, 2024). "Compared to controls, age-dependent penetrance in All CHEK2 variants for all cancers was significantly different in both MyCode (adjusted HR: 1.26 [95%CI 1.17-1.36], P-value: 6.1×10−10) and UKBB (adjusted HR 1.31 [95%CI 1.24-1.40], P-value: 2.0×10−16)." (PMID 39371170, 2024). "In the overall MaBC and FBC cohorts, we compared mutational prevalence in cancer susceptibility genes (CSG) (ATM/BRCA1/BRCA2/CHEK2/PALB2)." (PMID 39049124, 2024). "We further compared mutational signatures occurring in the CHEK2-deficient cancers to those in a cohort of (mostly) sporadic cancers (n = 7515) from TCGA of various tissue origins (available online)." (PMID 38848470, 2024). "CHEK2 PMV or PTV heterozygotes alone were at higher risk for all cancers tested compared to controls in both MyCode and UKBB." (PMID 39371170, 2024). "We analyzed the genomes, using shallow whole-genome sequencing (sWGS) and whole-exome sequencing (WES), from 16 cancers of 9 individuals homozygous for the most common loss-of-function (LoF) gPV in CHEK2 (NM_007194.4; c.1100del)." (PMID 38848470, 2024). "CHEK2 plays a crucial role in DNA damage response and cell cycle regulation, and mutations in this gene can increase cancer risk." (PMID 38332687, 2024). "In this study, we analyzed CHEK2 variants in a group of people from Türkiye who had a cancer diagnosis or family history of cancer and investigated how CHEK2 variations increase cancer risk." (PMID 39594831, 2024). "SBS3, the HRD-related mutational signature, was observed to some level in 13% (2/16) of CHEK2-deficient cancers, and it was the predominant mutational signature (86%, 24/28) in the BRCA1/2-deficient group (P < .001)." (PMID 38848470, 2024). "Intriguingly, they also demonstrate that the spectrum of mutational signatures of CHEK2-deficient tumors resembles that of sporadic tumors more so than what is observed in BRCA-deficient cancers." (PMID 38950525, 2024). "At the same time, CHEK2 GPV are also associated with increased risk of multiple other cancer types including colorectal, thyroid, pancreatic, kidney or hematological malignancies, reviewed in Ref." (PMID 38554551, 2024).